SERTAD3 (SERTA domain containing 3)
Description:
Antiviral interferon-stimulated protein that plays a role in innate immunity and in the suppression of viruses through different mechanisms. Plays a role in the late phase response of TLR-induced immune effector expression (By similarity). During influenza infection, interacts with PB2, PB1, and PA to disrupt the formation of the viral RdRp complex. Inhibits zika virus by interacting with the capsid protein in the nucleolus and reducing its abundance through proteasomal degradation. Strong transcriptional coactivator.
Synonyms: RBT1
Tractability: PROTAC: ubiquitination databases record sites on it.
Gene: Protein-coding gene on chromosome 19 (40,440,642 to 40,445,114, reverse strand). Ensembl gene ENSG00000167565.
Subcellular location: Nucleus
Subcellular location (Human Protein Atlas): Nucleoli
Gene Ontology:
Molecular function: protein binding
Biological process: negative regulation of cell growth; regulation of DNA-templated transcription; positive regulation of DNA-templated transcription
Cellular component: nucleus
Genetic constraint (gnomAD): Loss-of-function variants: 6 observed, 10.29 expected, observed/expected ratio (o/e) 0.58, 90% interval 0.32 to 1.15. The upper end of that interval is the gene's LOEUF score, 1.15, which puts it in group 5 of 6, group 1 being the genes least tolerant of losing a copy. Missense variants: 261 observed, 230.47 expected, observed/expected ratio (o/e) 1.13, 90% interval 1.02 to 1.25. Synonymous variants: 101 observed, 93.68 expected, observed/expected ratio (o/e) 1.08, 90% interval 0.92 to 1.27.
Homologues: Orthologues: chimpanzee SERTAD3 (100% identical), macaque SERTAD3 (99% identical), dog SERTAD3 (93% identical), pig SERTAD3 (91% identical), guinea pig SERTAD3 (87% identical), mouse Sertad3 (86% identical), rat Sertad3 (84% identical). Paralogues in human: SERTAD1 (36% identical).
Diseases named in the same sentence as SERTAD3 in open-access papers:
SERTAD3 is named in the same sentence as 10 diseases in open-access papers, as found by Europe PMC text mining. Sharing a sentence is not in itself a finding about the gene and the disease. The quoted sentences say what the papers report.
breast carcinoma (3 papers, 2012 to 2024). "SERTAD3 is a pro-cancer gene located within the 19q13 amplicon that has been shown to inhibit the growth of breast cancer cells and enhance tumor sensitivity to treatment with the drug tamoxifen." (PMID 39376611, 2024). "SERTAD3 is homologous to SERTAD1 and is up-regulated in MCF7 breast cancer cell lines (FANTOM5)." (PMID 27632927, 2016).
virus infection (2 papers, 2020 to 2023). "SERTAD3 has been shown to be a transcriptional coactivator, with expression elevated in cancer cell lines, but very little other information is known about the role of this protein, particularly during virus infections." (PMID 31947814, 2020). "Additionally, immunofluorescence staining of SERTAD3 with PB1, PB2 or PA following virus infection revealed that all three of these proteins co-localized with SERTAD3 in the nucleoli." (PMID 37112812, 2023).
retinoblastoma (1 paper, 2024). A malignant tumor that originates in the nuclear layer of the retina. "Again a proportion of retinoblastoma showed diffuse-growing, plaque-shaped multifocal tumors, but the association with KAL1 and SERTAD3 was not validated." (PMID 37615761, 2024).
cancer (4 papers, 2009 to 2024). A tumor composed of atypical neoplastic, often pleomorphic cells that invade other tissues. "Others that have been indirectly linked to cancer include HIST1H2AD, two zinc finger proteins (ZCCHC3, ZNF552), and CSRP2, CREBL2, and SERTAD3." (PMID 29282095, 2017).
tumor (3 papers, 2020 to 2024). "SERTAD3 has the potential to contribute to tumor growth by inducing E2F activity." (PMID 34490033, 2021).
bacterial infections (1 paper, 2022). "Comparison of these results with those obtained from bacterial infections showed genes associated with cell‐cycle progression and cell proliferation (RGCC, SENP5, SMC6, SERTAD3, MAD2L1BP) to be specifically upregulated in DC3s." (PMID 34333764, 2022).
SERTAD3 also shares sentences with these, for which no sentence is quoted: infection (2 papers); candidiasis (1); Cirrhosis (1); ovarian carcinoma (1).